RAB5B (RAB5B, member RAS oncogene family)
Description:
The small GTPases Rab are key regulators of intracellular membrane trafficking, from the formation of transport vesicles to their fusion with membranes. Rabs cycle between an inactive GDP-bound form and an active GTP-bound form that is able to recruit to membranes different sets of downstream effectors directly responsible for vesicle formation, movement, tethering and fusion. Involved in early endocytic trafficking. Required for EEA1 recruitment to early endosomes. Required for EGF and transferrin endocytosis and trafficking through early endosomes.
Tractability: Small molecule: a structure with a bound ligand is known; it has a binding pocket of medium quality. Antibody: UniProt places it where antibodies can reach, with high confidence; its Gene Ontology location is reachable by antibodies, with high confidence. PROTAC: ubiquitination databases record sites on it; its protein half-life has been measured.
Target class: Enzyme; Hydrolase
Gene: Protein-coding gene on chromosome 12 (55,973,913 to 55,996,683, forward strand). Ensembl gene ENSG00000111540.
Subcellular location: Cell membrane; Early endosome membrane; Melanosome
Subcellular location (Human Protein Atlas): Vesicles
Pathways (Reactome):
Vesicle-mediated transport: Clathrin-mediated endocytosis; RAB GEFs exchange GTP for GDP on RABs; TBC/RABGAPs
Disease: Respiratory syncytial virus (RSV) attachment and entry
Immune System: Neutrophil degranulation
Metabolism of proteins: RAB geranylgeranylation
Gene Ontology:
Molecular function: G protein activity; GDP binding; GTP-dependent protein binding; GTPase activity; protein binding; GTP binding
Biological process: antigen processing and presentation; endocytosis; endosomal transport; plasma membrane to endosome transport
Cellular component: early endosome membrane; endosome; extracellular exosome; melanosome; plasma membrane; early endosome; endocytic vesicle; membrane; secretory granule membrane; synaptic vesicle membrane
Genetic constraint (gnomAD): Loss-of-function variants: 8 observed, 27.08 expected, observed/expected ratio (o/e) 0.3, 90% interval 0.17 to 0.53. The upper end of that interval is the gene's LOEUF score, 0.53, which puts it in group 2 of 6, group 1 being the genes least tolerant of losing a copy. Missense variants: 164 observed, 271.48 expected, observed/expected ratio (o/e) 0.6, 90% interval 0.53 to 0.69. Synonymous variants: 89 observed, 101.56 expected, observed/expected ratio (o/e) 0.88, 90% interval 0.74 to 1.04.
Homologues: Orthologues: chimpanzee RAB5B (100% identical), guinea pig RAB5B (100% identical), mouse Rab5b (100% identical), rabbit RAB5B (100% identical), macaque RAB5B (99% identical), rat Rab5b (99% identical), dog RAB5B (99% identical), tropical clawed frog rab5b (93% identical), pig RAB5B (69% identical). Paralogues in human: RAB5C (84% identical), RAB5A (81% identical), RAB17 (41% identical), RAB11B (40% identical), RAB11A (40% identical), RAB22A (40% identical), RAB1A (39% identical), RAB1B (38% identical), RAB26 (38% identical), RAB31 (38% identical), RAB6B (38% identical), RAB7A (38% identical), and 56 more.
Diseases named in the same sentence as RAB5B in open-access papers:
RAB5B is named in the same sentence as 41 diseases in open-access papers, as found by Europe PMC text mining. Sharing a sentence is not in itself a finding about the gene and the disease. The quoted sentences say what the papers report.
breast carcinoma (11 papers, 2017 to 2025). "By knocking down RAB5B in MCF-7and SK-Hep-1cells, it is strongly proved that RAB5B significantly inhibits the proliferation and migration of breast cancer cells, highlighting its potential as a target for anti-breast cancer drugs." (PMID 40842984, 2025). "This study focuses on the role of RAB5B gene in the function of breast cancer cells, especially its influence on cell viability and migration potential." (PMID 40842984, 2025). "The RAB5B gene was successfully knocked out in breast cancer cell lines using siRNA technology, and the corresponding cell deletion model was constructed." (PMID 40842984, 2025). "Another circulating miRNA, miR-130a-3p, was reported to be under-expressed in the exosomes isolated from breast cancer patients with advanced staging, and this miRNA was found to be able to suppress RAB5B to reduce the breast cancer cell stemness." (PMID 36674525, 2023). "The overexpression of miR-130a-3p in breast cancer stem-cell-like cells suppresses proliferation and migration by targeting RAB5B, member of the RAS oncogene family (RAB5B)." (PMID 36612314, 2023). "In contrast, exosomal miR-130a-3p suppressed breast cancer stem cell proliferation, invasion and migration by targeting RAB5B, a RAB family GTPase." (PMID 32646059, 2020). "MiR-130a-3p inhibits human breast cancer stem-like cell migration and invasion by regulating RAB5B." (PMID 41361055, 2025). "Conversely, knockdown of RAB5B inhibits breast cancer cell proliferation, migration, and invasion." (PMID 40080350, 2025). "In addition, the research results show that methotrexate has shown remarkable efficacy in the treatment of breast cancer, which suggests that the treatment strategy for RAB5B may provide a new direction for drug development of some cancers." (PMID 40842984, 2025). "RAB5B has been shown to be activated in malignant melanoma, while RAB5C enhances epidermal growth factor-induced progression of breast cancer." (PMID 28103577, 2017). "Normal breast tissue exhibited significantly higher levels of exosomal miR-130a-3p as compared to breast cancer tissue samples; however, no in vivo assays were performed with miR-130a-3p or RAB5B." (PMID 32646059, 2020).
melanoma (6 papers, 2014 to 2025). A malignant, usually aggressive tumor composed of atypical, neoplastic melanocytes. "The expression level of RAB5B is particularly significant in the immune cell subtypes of basal cell carcinoma and melanoma." (PMID 40842984, 2025). "Just as in the WNT5A induced malignant melanoma exosomes, Rab5b was expressed in plasma-derived exosomes from malignant melanoma patients." (PMID 24766647, 2014). "Also, Rab5b was recently shown to participate in exosome-formation in malignant melanoma cells." (PMID 24766647, 2014). "Specifically RAB5B and RAB27 were shown to increase the release and transfer capability of the microvesicles being involved in tumor metastatization including melanoma." (PMID 26912358, 2016). "We previously developed a similar assay to detect and quantify plasma exosomes expressing Rab5B/CD63 or Rab5B/caveolin plasma exosomes and demonstrated that CD63+ exosomes or caveolin-1+ exosomes were significantly increased in melanoma and prostate cancer patients as compared to healthy donors." (PMID 32231660, 2020).
malaria (4 papers, 2014 to 2025). Malaria is a serious and sometimes fatal disease caused by a parasite that commonly infects a certain type of mosquito which feeds on humans. "Recent attempts to generate a deletion mutant of N-terminally myristoylated and palmitoylated Rab5b in the rodent malaria parasite P. berghei (PBANKA_140910) were unsuccessful, suggesting that PbRab5b is essential for the asexual blood stage of the parasite." (PMID 27316546, 2016). "We targeted the orthologous rab5b gene of the rodent malaria parasite P. berghei for gene deletion using standardized transfection methods." (PMID 24498355, 2014). "To test whether the core malaria parasite HOPS/CORVET complex might function in early endosomes, we co-localized VPS11 with Rbns5 and Rab5b, proteins known to be critical for the delivery of endocytosed hemoglobin via early endosomes to the DV." (PMID 40198740, 2025).
colorectal cancer (3 papers, 2020 to 2023). A primary or metastatic malignant neoplasm that affects the colon or rectum. "The following mechanistic studies show that lncRNA-APC1 reduces exosome production in colorectal cancer cells by reducing Rab5b mRNA stability, and this effect inhibits tumor angiogenesis by inhibiting the over-activation of the MAPK pathway in endothelial cells." (PMID 37602326, 2023). "In colorectal cancer cells, lncRNA-APC1 binds to Rab5b mRNA, leading to reduced stability of this mRNA and decreased RAB5B protein levels." (PMID 36905871, 2023). "In colorectal cancer, activation of the Adenomatous Polyp in Colon (APC) gene of lncRNA (lncRNA APC1) can directly affect the stability of Rab5b mRNA, thereby inhibiting exosome production by CRC cells and ultimately tumor angiogenesis." (PMID 37602326, 2023).
type 2 diabetes (3 papers, 2016 to 2023). "Six out of twenty selected genes with largest expression difference (CYP1B1, GPT), genes linked to PCOS (RAB5B) or type 2 diabetes (PPARG, SVEP1), and methylation (DMAP1) were replicated in a separate case-control study." (PMID 26975253, 2016).
asthma (2 papers, 2018 to 2024). "After comparison, asthma and GERD were found to share six genes (ERBB3, RBM6, HLA-B, SDK1, RERG, RAB5B), one of which, ERBB3, was also significantly associated with both eczema and GERD." (PMID 39223263, 2024). "The MAGMA analysis identified a distinct signal at locus 12q13.2 that is associated with both asthma and GERD and also corresponds to two pleiotropic genes (i.e., RAB5B and ERBB3) identified in the gene-based MAGMA results." (PMID 39223263, 2024). "There were common genes between these two study groups, where five genes were up-regulated (ATP5E, BRK1, KCNJ6, RNASEH2C, and RPL9) and one gene (RAB5B) was down-regulated in patients with mild and severe asthma compared with normal individuals." (PMID 30038057, 2018). "Furthermore, we obtained regional association plots close to these six shared genetic loci from FUMA and confirmed that one common locus at 12q13.2 (where RAB5B and ERBB3 are located) is associated with asthma and GERD." (PMID 39223263, 2024).
type 1 diabetes (2 papers, 2015 to 2023). "Given RAB5B’s association with type 1 diabetes it is possible that genes in this locus play a regulatory role via that impacts beta cell function or insulin secretion, a process that is impaired in both disorders." (PMID 26305227, 2015). "RAB5B has also been identified as a susceptibility locus for type 1 diabetes and childhood obesity." (PMID 26305227, 2015).
atherosclerosis (1 paper, 2019). A disease characterized by the build-up of fatty material and calcium deposition in the arterial wall resulting in partial or complete occlusion of the arterial lumen. "Thus, we summarized a model that increased plasma level of miR-575 in essential hypertensive patients with atherosclerosis suppresses angiogenesis processes including migration, proliferation, and apoptosis of endothelial cells via targeting Rab5B and MEK-ERK signaling pathways." (PMID 30333257, 2019). "We further demonstrated the crucial effects of miR-575 on migration, proliferation, and apoptosis of endothelial cells through Rab5B-mediated MAPK signaling pathway, providing the potential role of miR-575 as a biomarker or therapeutic target for atherosclerosis in hypertensive patients." (PMID 30333257, 2019).
autoimmune thyroid disease (1 paper, 2025). Inflammatory disease of the thyroid gland due to autoimmune responses leading to lymphocytic infiltration of the gland. "GSEA results revealed that high RAB5B expression is closely linked to immune regulation and stress response, including humoral immune responses mediated by circulating immunoglobulins, cellular responses to unfolded proteins, and autoimmune thyroid diseases." (PMID 40842984, 2025).
glaucoma (1 paper, 2020). Increased pressure in the eyeball due to obstruction of the outflow of aqueous humor. "Moreover, we identified Rab5b, App, Stx16, Pikfyve, Dnaja3, Cltc and Dlg4 as key genes impacting glaucoma pathogenesis by transcription differences." (PMID 33133146, 2020).
Insulin resistance (1 paper, 2019). Increased resistance towards insulin, that is, diminished effectiveness of insulin in reducing blood glucose levels. "A previous study implicated that the expression of RAB5B gene in skeletal muscle is increased 2–3 times in subjects with insulin resistance." (PMID 31036605, 2019). "Consistently, RAB5B gene could increase insulin resistance via reducing the function of glucose transporter-4 (GLUT4) on the plasma mucosal surface." (PMID 31036605, 2019).
interstitial lung disease (1 paper, 2022). A diverse group of lung diseases that affect the lung parenchyma. "This function was revealed from investigation of a proband with interstitial lung disease suggestive of a surfactant dysfunction disorder who carried a de novo Asp136His variant in the RAB5B gene." (PMID 35121658, 2022).
leishmaniasis (1 paper, 2022). Infectious disease that is transmitted through the bite of hematophagous female phlebotomine sand flies. "Furthermore, apart from the fact that HbR is a novel vaccine candidate against leishmaniasis, it is also worth exploring Rab5b null mutant parasites as a vaccine candidate." (PMID 35631106, 2022).
metastatic cancer (1 paper, 2019). A carcinoma which has spread from the original site of growth to another anatomic site. "Our data suggested that down-regulation of Rab5B by siRNA or overexpression of miR-575 inhibit cell migration and proliferation which is consistent with Rab5 activity in the metastatic cancer cells." (PMID 30333257, 2019).
nasal polyps (1 paper, 2025). "RAB5B-related diseases are explored on openttarget, and the bubble diagram shows that RAB5B is related to nasal polyps and neurodegenerative diseases." (PMID 40842984, 2025).
osteoporosis (1 paper, 2022). A condition of reduced bone mass, with decreased cortical thickness and a decrease in the number and size of the trabeculae of cancellous bone (but normal chemical composition), resulting in increased fracture incidence. "Together, these 4 core proteins (GSTP1, LAMP2, COPB1, and RAB5B) may account for osteoporosis with iron accumulation, and potentially be a serum marker for it." (PMID 36313751, 2022). "We ultimately identified 4 core proteins (GSTP1, LAMP2, COPB1, RAB5B) that were significantly differentially expressed in the bone of osteoporosis patients with iron accumulation, and validated the changed protein level in the serum of the medical examination population." (PMID 36313751, 2022). "Therefore, we speculate that these 4 DEPs (GSTP1, LAMP2, COPB1, RAB5B) may be novel candidate core proteins of osteoporosis with iron accumulation." (PMID 36313751, 2022). "Finally, we screened four candidate proteins of osteoporosis with iron accumulation, GSTP1, LAMP2, COPB1, and RAB5B." (PMID 36313751, 2022).
pituitary tumor (1 paper, 2025). A benign or malignant neoplasm affecting the pituitary gland. "In the pituitary tumor cohort (GSE169498), we identified a total of five MRGs (MED27, RARRES2, AKAP8L, RAB5B, and STK39) that are associated with the invasiveness of pituitary tumors." (PMID 40873641, 2025).
skin melanoma (1 paper, 2025). "At the same time, in GSE 72056 skin melanoma data set containing 4645 single cell samples, RAB5B was highly expressed in depleted Endothelial cell and monocytes in skin melanoma microenvironment." (PMID 40842984, 2025). "In addition, the spatial transcription data on SpatialDB showed that RAB5B spatially overlapped with endothelial cell markers PECAM1 and VWF in BCC cancer tissues and M2 macrophage markers CD68 and CD163 in skin melanoma tissues." (PMID 40842984, 2025).
urinary system tumors (1 paper, 2025). "Especially in the field of urinary system tumors, it is confirmed that RAB5B is a reliable and effective prognostic marker for predicting the response to anti-PD-1 immunotherapy." (PMID 40842984, 2025).
viral myocarditis (1 paper, 2025). Myocarditis that is caused by an infection with a viral agent. "In KICH, RAB5B is a positive regulator of renal water homeostasis and viral myocarditis." (PMID 40842984, 2025).
tumor (13 papers, 2009 to 2025). "Although studies have revealed the functional mechanisms of RAB5B in specific tumor types, its role in pan-cancer and the underlying molecular mechanisms still lack in-depth analysis." (PMID 40842984, 2025). "Conversely, RAB5B expression was positively correlated with neutrophil infiltration levels in B cells, tumor-associated fibroblasts, endothelial cells, CD4+ T cells, and mast cells." (PMID 40842984, 2025). "Gene_DE module 2.0 (TIMER 2.0) deciphered associations between RAB5B expression and tumor-infiltrating immune cell subsets." (PMID 40842984, 2025). "The relationship between immune cell infiltration and RAB5B expression was thoroughly investigated to elucidate the association between RAB5B and tumor immunity." (PMID 40842984, 2025). "We designed an in-house sandwich ELISA (Exotest) to capture and quantify exosomes in plasma based on expression of housekeeping proteins (CD63 and Rab-5b) and a tumor-associated marker (caveolin-1)." (PMID 19381331, 2009). "In some, high RAB5B expression correlates with tumor malignancy, poor prognosis, and drug resistance, while in others, it may act as a tumor suppressor, with downregulation linked to tumor development." (PMID 40842984, 2025). "The results showed that there was a significant correlation between the expression level of MMR gene and the expression level of RAB5B in all types of tumor samples." (PMID 40842984, 2025). "Further exploration of the TISCH single-cell database revealed that the expression of RAB5B is primarily concentrated in specific cell types within the tumor immune microenvironment, especially endothelial cells and immune cells." (PMID 40842984, 2025). "Pan-cancer analysis reveals notable associations between RAB5B expression and TMB levels across 11 malignancies, as well as MSI status in 4 tumor types." (PMID 40842984, 2025). "The TISCH database identified primary cell types expressing RAB5B within the tumor microenvironment, while univariate Cox regression modeling evaluated its prognostic significance in cancer outcomes." (PMID 40842984, 2025). "Evidence suggests that RAB5B modulates tumor progression, prognostic potential, and therapeutic efficacy through dynamic interactions with immune cell populations, highlighting its role as a regulatory node in immune-tumor crosstalk." (PMID 40842984, 2025). "RAB5B inhibits ectopic metastasis of tumor cells mainly by regulating the process of cell adhesion and migration." (PMID 40842984, 2025). "The generated thermogram showed that most immune response genes were co-expressed with RAB5B, and were positively correlated with RAB5B in all tumor types except BLCA, BRCA, GBM, LGG, MESO, SARC and THCA." (PMID 40842984, 2025). "In our research, the key role of RAB5B in tumor immunity has been clearly verified." (PMID 40842984, 2025). "In some tumor cells, the abnormal expression of RAB5B may disturb the intracellular material transport system, and then have a far-reaching impact on the malignant behaviors such as cell proliferation, apoptosis, invasion and migration." (PMID 40842984, 2025). "This hypothesis provides new clues and ideas for us to further explore the specific mechanism of RAB5B in the process of tumor immunity." (PMID 40842984, 2025). "In cancer, the regulatory effect of RAB5B on autophagy may directly or indirectly affect the proliferation, apoptosis and drug resistance of tumor cells." (PMID 40842984, 2025). "In some cancers, the expression level or active state of RAB5B may change, which affects the efficiency and accuracy of vesicle transport, and then promotes the proliferation, migration and invasion of tumor cells." (PMID 40842984, 2025). "In many tumor types, the expression of RAB5B is positively correlated with the infiltration level of neutrophils in B cells, Cancer-Associated Fibroblasts, Progenitor cells,endothelial cells, Dendritic Cell, CD4+ T cells,mast cells,Monocyte, Neutrophils and Treg." (PMID 40842984, 2025).